SENP3 (SUMO specific peptidase 3)
Diseases named in the same sentence as SENP3 in open-access papers (continued):
Sharing a sentence is not in itself a finding about the gene and the disease.
acute lung injury (1 paper, 2025). A condition of lung damage that is characterized by bilateral pulmonary infiltrates (pulmonary edema) rich in neutrophils, and in the absence of clinical heart failure. "SUMO-specific peptidase 3 (SENP3) is a deSUMOylating enzyme that is abundantly produced in response to ROS during acute lung injury (ALI)." (PMID 39910395, 2025).
allergic rhinitis (1 paper, 2023). Inflammation of the nasal mucous membranes caused by an IgE-mediated response to external allergens. "Meanwhile, the number of CD206+M2 significantly increased in the allergic rhinitis model constructed using SENP3 knockout mice and controls, with a more obvious proliferation of the nasal mucosa." (PMID 36840491, 2023). "Models of allergic rhinitis were constructed using Senp3 cKO mice (N = 5) and Senp3 fl/fl mice (N = 4) to further confirm the hypothesis that Senp3 cKO promoted the formation of NPs by affecting M2 polarization." (PMID 36840491, 2023). "An animal model of allergic rhinitis was constructed using SENP3 knockout mice." (PMID 36840491, 2023).
amyotrophic lateral sclerosis (1 paper, 2023). Amyotrophic lateral sclerosis (ALS) is a neurodegenerative disease characterized by progressive muscular paralysis reflecting degeneration of motor neurons in the primary motor cortex, corticospinal tracts, brainstem and spinal cord. "In cachexia, particularly in denervation-induced cachexia in amyotrophic lateral sclerosis (ALS), the SENP3-dependent transcriptional pathway was targeted." (PMID 36831310, 2023).
aortic aneurysmal diseases (1 paper, 2025). "A better understanding of the role of SENP3 and CTH in AAA may ultimately lead to new approaches to prevent and treat aortic aneurysmal diseases." (PMID 40019399, 2025).
Atherosclerotic lesion (1 paper, 2025). A lesion associated with atherosclerosis, a multifactorial and multipart progressive disease manifested by the focal development within the arterial wall of lesions, that ranges from the development of a fatty streak, plaque progression, and plaque disruption. "In this study, we demonstrate that SENP3 is significantly upregulated in human and mouse atherosclerotic lesions and in VSMCs exposed to pro-atherogenic stimuli." (PMID 41307849, 2025).
Autoimmunity (1 paper, 2018). The occurrence of an immune reaction against the organism's own cells or tissues. "Our work provides deep insights into the regulation and function of SENP3-mediated deSUMOylation in autoimmunity and antitumor immunity." (PMID 30089837, 2018).
bladder cancer (1 paper, 2022). "Taken together, SENP3 promotes bladder cancer proliferation and EMT transformation by regulating STAT3." (PMID 36227136, 2022). "Meanwhile, SENP3 promoted the phosphorylation of STAT3 to address the relationship between SENP3 and STAT3 in bladder cancer, SENP3 and STAT3 proteins were detected in 8 cases of bladder cancer and para-cancerous tissues." (PMID 36227136, 2022). "Taken together, SENP3 protein level is up-regulated in bladder cancer, which is correlates with protein expression of STAT3 and p-STAT3." (PMID 36227136, 2022). "STAT3 has been reported to be SUMOylation in tumors, and SENP3 expression in bladder cancer tissue was higher than that in adjacent or normal tissue." (PMID 36227136, 2022). "In all, this study tested STAT3 and SENP3 expression in bladder cancer tissues and examined its connection and molecular mechanism in bladder cancer." (PMID 36227136, 2022). "This study found that SENP3 induced deSUMOylation of STAT3 remarkably promote bladder cancer proliferation and EMT." (PMID 36227136, 2022). "In our study, we examined the regulation of STAT3 post-translational modifications (PTMs) and found that SENP3 is high in bladder cancer." (PMID 36227136, 2022). "When we assessed the effect of SENP3 expression in bladder cancer patients (400 samples), the probability of cancer progression was found to be statistically significant with low SENP3 expression as compared to that of high SENP3 expression." (PMID 36227136, 2022). "Moreover, SENP3 promoted the proliferation of bladder cancer cells." (PMID 36227136, 2022). "The results showed that the expression levels of SENP3, STAT3 and p-STAT3 in bladder cancer tissues were higher than para-cancerous normal tissues." (PMID 36227136, 2022). "SENP3/STAT3/PYCR1 pathway promoted the viability, proliferation, invasion and EMT of bladder cancer cells." (PMID 36227136, 2022). "We sought to clarify how SENP3 affects PYCR1 and STAT3 to regulate the development of bladder cancer." (PMID 36227136, 2022). "SENP3 is widely involved in a variety of diseases, including tumors, and has not been reported in bladder cancer." (PMID 36227136, 2022). "The results provide novel insights into the regulation of SENP3/STAT3/PYCR1 pathway, which has key roles in bladder cancer progression and may aid in identifying new biomarkers or targeted therapies for bladder cancer." (PMID 36227136, 2022). "Here, we found that SENP3 expression was higher in bladder cancer tissues than in normal tissues." (PMID 36227136, 2022).
Cachexia (1 paper, 2020). Severe weight loss, wasting of muscle, loss of appetite, and general debility related to a chronic disease. "The expression level of SENP3 is degraded during cachexia, which is characterized by the tremendous loss of sarcomeric proteins, especially MyHC-II." (PMID 33192553, 2020). "In cachexia, SENP3 regulation of SETD7 is impaired, causing altered MyHC-II expression and disorganized sarcomeres." (PMID 33192553, 2020).
colon adenocarcinoma (1 paper, 2014). "SENP3 has been identified to accumulate in a variety of types of primary human cancer, including colon adenocarcinoma, by modulating the SUMOylation status of the tumor suppressor, promyelocytic leukemia protein (PML)." (PMID 24926368, 2014).
fibrosarcoma (1 paper, 2024). A malignant mesenchymal fibroblastic neoplasm affecting the soft tissue and bone. "To confirm that SENP3 regulates ferroptosis through FSP1, we used HT1080, a widely used fibrosarcoma cell line that is commonly used in ferroptosis studies." (PMID 39025016, 2024).
Hepatic steatosis (1 paper, 2016). Steatosis is a term used to denote lipid accumulation within hepatocytes. "The top three genes (apoe, a2m and tnfrsf11b) were found to be regulated by SENP3 in hepatic steatosis in vitro." (PMID 27853276, 2016). "It was confirmed that increased lipid accumulation in FFA-treated hepatocytes was attenuated or enhanced with SENP3 silencing or overexpression, respectively, arguing for the regulation of hepatic steatosis by SENP3." (PMID 27853276, 2016). "A model of hepatic steatosis was established in cultured hepatocytes to further explore the role of SENP3 in NAFLD in vitro." (PMID 27853276, 2016). "Thus, the data delineated that SENP3 activity contributes to the severity of steatosis, suggesting a potential novel therapeutic target for the management of hepatic steatosis." (PMID 27853276, 2016). "The focus of the current study was to investigate whether SENP3 contributes to lipid metabolism in NAFLD, based on our unexpected preliminary observation that SENP3 is up-regulated in fatty liver." (PMID 27853276, 2016).
lung adenocarcinoma (1 paper, 2023). A carcinoma that arises from the lung and is characterized by the presence of malignant glandular epithelial cells. "Overexpression of SENP1 has also been shown to be involved in lung adenocarcinoma progression, and SAE1, UBC9, and SENP3 are remarkably upregulated in lung adenocarcinoma and are associated with poor prognosis." (PMID 37123398, 2023).
myocardial infarction (1 paper, 2021). Gross necrosis of the myocardium, as a result of interruption of the blood supply to the area, as in coronary thrombosis. "Redox sensing SENPs, i.e. SENP1 and SENP3 obviously play a role in ROS dependent ischemia reperfusion injury of the heart, and a striking significance emerges for SENP2 in regulating cardiomyocyte proliferation and cardiac regeneration after myocardial infarction." (PMID 34869605, 2021).
nasal polyps (1 paper, 2023). "Downregulation of SENP3 promotes the formation of nasal polyps mediated by increasing alternative activated macrophage in nasal mucosal inflammation." (PMID 36840491, 2023). "However, the role of ROS and SENP3 in the formation of nasal polyps (NPs) remains unclear." (PMID 36840491, 2023).
oral squamous cell carcinoma (1 paper, 2013). "In the present study, we analysed the expression of SENP3 in human oral squamous cell carcinoma (OSCC) and investigated the correlation between its expression and clinicopathological parameters in OSCC patients." (PMID 23467634, 2013).
osteosarcoma (1 paper, 2022). A usually aggressive malignant bone-forming mesenchymal neoplasm, predominantly affecting adolescents and young adults. "In relation to this, it has also been shown that SENP3 overexpression in osteosarcoma cells results in inhibited expression of the epithelium-associated gene CDH1, which courses with promoter hypermethylation." (PMID 35887358, 2022). "Database analysis indicates that in general SENP3 is abundantly expressed in sarcoma and high expression correlates with poor prognosis, being shown in osteosarcoma that SENP3 depletion results in impaired proliferation, migration and invasion, and in enhanced apoptosis." (PMID 35887358, 2022). "Thus, SENP3 has been suggested as a powerful biomarker for osteosarcoma diagnosis." (PMID 35887358, 2022).
pancreatic adenocarcinoma (1 paper, 2021). "For example, LAS1L and SENP3, as components of the MLL1-WDR5 super complex, regulate pancreatic adenocarcinoma gene transcription by affecting chromatin remodelling." (PMID 33976726, 2021).
peritonitis (1 paper, 2024). Inflammation of the peritoneum (tissue that lines the abdominal wall and covers most of the organs in the abdomen). "To test whether SENP3 drives ferroptosis of macrophages in vivo, we used a mouse model of zymosan-induced sterile peritonitis followed by RSL3 injection, in which RSL3 was injected 72 h after zymosan treatment, and the peritoneal macrophages were mainly M2 macrophages." (PMID 39025016, 2024).
renal cell carcinoma (1 paper, 2020). "We can see that SENP5, SENP3, UBE2I, PIAS3, TRIM27, SAE1, and CBX4 are risk factors in the development of renal cell carcinoma." (PMID 33123273, 2020).
steatosis (1 paper, 2016). Increased lipid within the cytoplasm of cells. "However, the precise underlying mechanism of SENP3 in steatosis will be determined in future experiments, using SENP3 liver-specific knockout mice." (PMID 27853276, 2016). "Collectively, these data suggest that SENP3 plays a critical role in steatosis." (PMID 27853276, 2016). "Moreover, SENP3-mediated steatosis occurs possibly via regulating downstream genes involved in abnormal lipid metabolism." (PMID 27853276, 2016). "Overall, these data provide further evidence that SENP3 plays an important role in steatosis." (PMID 27853276, 2016). "Thus, we believe that SENP3 likely acts in both paracrine and autocrine fashions during steatosis." (PMID 27853276, 2016). "However, the lack of a significant correlation between the severity of steatosis and hepatic SENP3 from NAFLD patients might be due to relatively small numbers of patients in this study and/or patient polymorphisms." (PMID 27853276, 2016).
viral infections (1 paper, 2019). "It is also possible that SENP3 may be a central viral stress sensor and protector of host translation—it responds to different viral infections by degrading IQGAP2 to boost Akt phosphorylation." (PMID 30640896, 2019).
tumor (38 papers, 2013 to 2026). "In human patients, we discovered that the levels of SENP3 were upregulated in the tumor-associated macrophages." (PMID 39123188, 2024). "Despite evidence of positive correlation between SENP3 levels and malignancy in a variety of cancers, it has been conversely reported that SENP3 loss also associates with tumor progression in other cancer types." (PMID 35887358, 2022). "We have previously shown that activating mitotic SENP3 by mutating the nine phosphorylation sites causes chromosome instability and promotes tumorigenesis in in vitro or in tumor-bearing nude mice models." (PMID 35869062, 2022). "To explore the effect of SENP3 loss on TAM function in tumor niches, we isolated TAM from the Py8119 transplants in Senp3 WT and cKO mice and analyzed the percentages of M1 and M2 macrophages within the TAM population." (PMID 33932085, 2022). "A lower level of SENP3 also appeared to be associated with advanced tumor stages and TNM grades, although the association was not statistically significant." (PMID 33932085, 2022). "The anti-CD8 antibody can deplete mitotic SENP3 activation-mediated anti-tumor effect, suggesting that CD8+ T cells play a critical role in mitotic SENP3 activation-associated anti-tumor immunity." (PMID 35869062, 2022). "High SENP7 expression also associates with advanced tumor stage, which inversely correlates with SENP3 expression." (PMID 35887358, 2022). "In this study, we find that the mutation of mitotic SENP3 phosphorylation in tumor cells can suppress tumor growth in immune-competent mouse model." (PMID 35869062, 2022). "SENP3 protein expression was higher in OSCC tissues compared to epithelial adjacent to tumor tissues, which indicated that SENP3 was associated with OSCC differentiation." (PMID 23467634, 2013). "Additionally, tumor-intrinsic SENP3 promotes the infiltration of tumor-associated macrophages (TAMs) while reducing cytotoxic T cells to facilitate immune evasion." (PMID 39755756, 2025). "Although tumor growth was significantly reduced after systematic treatment of the inhibitor, inhibition of Akt1 in M2 macrophage contributed to suppression of tumor growth, which was accelerated by SENP3 loss in macrophages." (PMID 33932085, 2022). "Mechanistically, in SENP3‐deficient macrophages, Akt1 becomes hyper‐SUMOylated, followed by its hyper‐phosphorylation and activation, which contributes to M2 polarization in the tumor environment." (PMID 33932085, 2022). "We further find that activating mitotic SENP3 by mutating the phosphorylation sites increases the formation of micronuclei, which enhance cGAS signaling-dependent innate immune response in tumor cells followed by stimulating host CD8+ T cell-mediated anti-tumor immunity in C57BL/6 mice." (PMID 35869062, 2022). "We have shown that mitotic SENP3 activation increases abnormal mitosis-caused chromatin instability, which leads to nucleus DNA strands releasing into the cytoplasm and the formation of micronucleus in tumor cells to activate cGAS signaling." (PMID 35869062, 2022). "The loss of SENP3 deSUMOylase activity in Tregs results in dysregulation T-cell homeostasis and SENP3 deficiency in macrophages facilitates macrophage polarization towards the pro-tumor M2 subtype." (PMID 34503213, 2021). "SENP3 knockdown significantly inhibited tumor growth and prolonged overall survival, the opposite results were observed in SENP3 overexpression group." (PMID 39755756, 2025). "We found that tumor-intrinsic SENP3 deficiency inhibited HCC tumor growth more strongly in C57BL/6 mice than in Nude mice, suggesting that SENP3-induced HCC tumorigenesis is partially mediated by immune function." (PMID 39755756, 2025). "As expected, the analysis of livers from DEN-CCl4-treated mice showed that SENP3 knockdown reduced tumor number and size, which confirms that targeting SENP3 has therapeutic potential during HCC progression." (PMID 39755756, 2025).
tumor (continued). "We observed that tumor-intrinsic SENP3 promotes the infiltration of TAMs, while reducing the accumulation of CD8+ T cells, resulting in an immunosuppressive microenvironment." (PMID 39755756, 2025). "Tissue microarray analysis showed that the HCC tumor tissues had higher SENP3 immunohistochemical (IHC) staining scores." (PMID 39755756, 2025). "In the subcutaneous tumor model, we observed that SENP3 knockdown reduced tumor volume and weight, and SENP3 overexpression exerted the opposite effect on tumor growth." (PMID 39755756, 2025). "In the liver orthotopic xenograft tumor model, SENP3 overexpression and knockdown promoted and inhibited the growth of intrahepatic HCC tumors, respectively." (PMID 39755756, 2025). "Overall, our study demonstrates the tumor-promoting role of SENP3 in HCC and that targeting SENP3 is a promising approach for HCC treatment." (PMID 39755756, 2025). "SENP3 expression was positively correlated with tumor size, microvascular invasion, TNM stage and Edmonson stage." (PMID 39755756, 2025). "We have previously implicated SENP7 in promoting cell survival after harmful OGD in tumor cells, showing an opposite effect to the SENP3 protease promoting cell death." (PMID 40348773, 2025). "Under oxidative stress, SENP3 accumulates in the cytoplasm of tumor cells, which triggers deSUMOylation of IFI204, a DNA sensor necessary for STING activation." (PMID 38280996, 2024). "Next, we evaluated their proliferation rates by the live-cell analysis system and observed that tumor cell lines require SENP3 for sustained proliferation." (PMID 39623295, 2024). "The secretome testing on the cell supernatant of the SENP3 deletion group indicated down-regulation of the anti-tumor factors (CCL5 and IL-β) and up-regulation of tumor-promoting factors (IL-10 and TGF-β)." (PMID 39123188, 2024). "SENP3 in macrophages is crucial for their anti-tumor function, and this study indicated its up-regulation during ESCC." (PMID 39123188, 2024). "Second, we did not establish PCa xenografts in situ in the animal experiments, thus the role of SENP3 in tumor microenvironment remains to be further explored." (PMID 39623295, 2024). "We indeed show that in two CDK6-dependent tumor cell models, depletion of SENP3 or SENP5 downregulates CDK6 and affects cell proliferation." (PMID 38065954, 2023). "SUMOylation-deficient DKC1, however, showed little effect on the inhibition of tumor migration upon SENP3 overexpression." (PMID 37188742, 2023). "Given that the integrated anti-tumor potency of SENP3 is enzymatically dependent, it is essential to explore its partners and potential substrates." (PMID 37188742, 2023). "To do so, we generated a mouse tumor cell line MC38 expressed with SENP3 wild-type (SENP3-WT) or mitotic SENP3 phosphorylation mutant (SENP3–9A, a mitotic activation form of SENP3)." (PMID 35869062, 2022). "Together, these data reveal that mitotic SENP3 activation in tumor cells can promote host anti-tumor immune response by coupling with cGAS signaling." (PMID 35869062, 2022). "These patients were also grouped as SENP3 high or SENP3 low based on their SENP3 mRNA level in those tumor tissues." (PMID 35869062, 2022). "Together, these data show that mitotic SENP3 activates cGAS signaling-mediated innate immune response in tumor cells." (PMID 35869062, 2022). "The expression of other M2 marker genes, including Arg‐1, IL‐10, CCL8, Fizz1 and YM‐1, were also upregulated in the tumor from Senp3 cKO mice, as demonstrated by qRT‐PCR analysis." (PMID 33932085, 2022). "The population of CD8+ T cells but not NK cells or CD4+ T cells in CD45+ cells from the SENP3–9A tumor tissues were much more than that from the SENP3-WT tumors in C57BL/6 mice." (PMID 35869062, 2022). "The findings further show that SENP3 is a positive factor to regulate anti-tumor immunity in tumor patients." (PMID 35869062, 2022).